CDX2 (caudal type homeobox 2)
Diseases named in the same sentence as CDX2 in open-access papers (continued):
Sharing a sentence is not in itself a finding about the gene and the disease.
rectal cancer (14 papers, 2012 to 2025). A primary or metastatic malignant neoplasm that affects the rectum. "This study also focused on risk prediction with CDX2 in rectal cancer, as there is less available literature on this, with most grouping colon and rectal cancers into one cohort." (PMID 39201360, 2024). "This is an important finding, as CDX2 cannot be recommended as a reliable predictor of neoadjuvant treatment and adjuvant chemotherapy efficacy in rectal cancer." (PMID 39201360, 2024). "Overall, our study findings align with the existing literature, providing further evidence for the correlation between low CDX2 expression and poorer overall survival in both colon and rectal cancers." (PMID 39201360, 2024). "Our study found that the percentages of CDX-2 and Ki-67 in low-grade rectal cancer were significantly higher than those in the medium to high-grade group." (PMID 37546428, 2023). "In our study, we found that CDX-2 was expressed in 100% of all rectal cancers, and the expression of CDX-2 in moderately and poorly differentiated carcinomas was significantly lower than that in well-differentiated carcinomas." (PMID 37749564, 2023). "Strong nuclear expression of caudal-type homeobox 2 (CDX2) was detected in primary rectal cancer cells." (PMID 36415832, 2022). "In our case, both the primary rectal cancer and metastasis splenic lesions showed caudal type homeobox 2 (CDX2) expression." (PMID 35960045, 2022). "Positive staining for caudal-type homeobox 2 (CDX2) was observed in both the primary tumor and metastatic lymph node, suggesting that the lymph node lesion was a metastasis of rectal cancer." (PMID 33388078, 2021). "CRC in the ascending colon and CDX2 expression loss have been identified as positive potential predictors of dMMR with rectal cancer as negative potential predictor of dMMR." (PMID 37325467, 2023). "We showed that low CDX2 expression was significantly correlated with poor prognostic features including lack of tumour differentiation, presence of lymphovascular or perineural invasion and poorer OS and DFS outcomes in both colon and rectal cancers." (PMID 39201360, 2024). "Adjuvant chemotherapy is an effective treatment option for rectal cancer patients, regardless of CDX2 expression status." (PMID 39201360, 2024). "The lack of significant differences in survival outcomes between patients with high and low CDX2 expression who received adjuvant chemotherapy for rectal cancer suggests that CDX2 expression likely does not predict response to chemotherapy in this population." (PMID 39201360, 2024). "Based on our findings, CDX2 is not a useful predictive biomarker for adjuvant chemotherapy in rectal cancer." (PMID 39201360, 2024). "There was an improvement in overall survival in rectal cancer patients who were treated with adjuvant chemotherapy regardless of high (p = 0.017) or low CDX2 expression (p < 0.0001)." (PMID 39201360, 2024). "Also, CDX2 was not evaluable in one other metastasis of rectal cancer that was negative for SATB2." (PMID 37349623, 2024). "Immunohistochemical staining showed that the specimen was positive for both cytokeratin 20 (CK20) and caudal-type homeobox 2 (CDX2) and negative for cytokeratin-7 (CK7), which indicated that it had originated from rectal cancer." (PMID 28748455, 2017). "Immunohistochemical staining showed the tumor to be positive for both CK20 and CDX2 and negative for CK7, indicating that it was a rectal cancer." (PMID 28748455, 2017). "In addition, all these tumors were negative for CDX-2; however, some androgen-independent prostate tumors display nuclear CDX2 staining, which could represent a potential dangerous pitfall for the differential diagnosis from rectal carcinoma." (PMID 28095874, 2017).
colorectal tumors (13 papers, 2012 to 2024). "In a multivariable analysis that adjusted for tumour stage, sex and location as confounding variables, the association between low-CDX2-expression colorectal tumours and a lower rate of overall survival remained significant." (PMID 39201360, 2024). "Gsdmd−/− /Cdx2-Cre+ /ApcF/+ mice developed significantly fewer colorectal tumors compared to Gsdmd+/−/Cdx2-Cre+/ApcF/+ controls, demonstrating a previously unreported role of GSDMD in promoting sporadic CRC development." (PMID 38898209, 2024). "were associated with prevention/protection against large intestine neoplasms, including GUCA2A, CDX2, VDR, VEFGA, GSTM1, HPGD, and PPARG." (PMID 37296943, 2023). "While it is well-established that colorectal tumors with CDX2 expression have better overall and cancer-specific survival rates, the prognostic impact of CDX2 on gynecological tumors, including UCS, is underexplored." (PMID 37200263, 2023). "Additionally, CDX2 is a potential marker for primary colorectal tumors, with most studies showing that CDX2 is a sensitive marker with a reported sensitivity of up to 90%." (PMID 39604765, 2024). "Furthermore, TTI-101 treatment also led to the upregulation of important genes such as GUCA2A, CDX2, VDR, GSTM1, HPGD, and PPARG that have been shown by others to be associated with the prevention of large intestine neoplasms." (PMID 37296943, 2023). "CDX2-negative CRCs are associated with a higher risk of recurrence and seem to benefit from adjuvant chemotherapy compared with CDX2-positive colorectal tumors." (PMID 37686649, 2023). "Among the CK7-/CK20- colorectal tumors CDX2 was positive in 16 of 17 (94%) cases." (PMID 22268990, 2012). "We also used a second mouse model of synchronized tumorigenesis in the colon that relies on tamoxifen-induced ablation of the Apc gene (Cdx2-Cre-ERT2+/ApcF/F mice), and allows for the study of early-stage colorectal tumors." (PMID 38898209, 2024).
melanoma (13 papers, 2013 to 2025). A malignant, usually aggressive tumor composed of atypical, neoplastic melanocytes. "A meta-analysis of six studies that investigated the association between five VDR polymorphisms (TaqI, FokI, BsmI, EcoRV, and Cdx2) and the risk of melanoma also showed that the Bsm1 genotype was associated with an increased risk of melanoma development." (PMID 30321335, 2019). "We identified 10 eligible studies that evaluated six VDR variants (Apa1, Bsm1, Cdx2, EcoRV, Fok1, and Taq1) in a total of 4,961 melanoma patients and 4,605 controls." (PMID 25887475, 2015). "This meta-analysis identified that the VDR variants Bsm1 and Fok1 are significantly associated with melanoma risk, whereas four other variants—Apa1, Cdx2, EcoRV, and Taq1—are not." (PMID 25887475, 2015). "The pooled estimates identified two variants—Fok1 and Bsm1—as significantly associated with melanoma risk, but not for the other four variants Apa1, Cdx2, EcorV and Taq1." (PMID 25887475, 2015). "Following a systematic review and meta-analysis of relevant published epidemiological studies to date, we have identified that the VDR variants Bsm1 and Fok1 are associated with the risk of developing melanoma, while four other variants (Apa1, Cdx2, EcoRV, and Taq1) are not." (PMID 25887475, 2015). "Furthermore, biomarkers such as TTF-1 and CDX-2 can be used to identify metastatic MCC, whereas LCA, CD99, S100, HMB-45, and SOX-10 can exclude lymphoma, Ewing sarcoma, and malignant melanoma." (PMID 41245381, 2025).
ovarian mucinous carcinoma (13 papers, 2008 to 2025). "We found that endogenous MDR1 expression was positively associated with CDX2 expression in ovarian mucinous adenocarcinoma." (PMID 27060927, 2016). "Loss of CDX2 expression is observed in poorly differentiated mucinous adenocarcinoma of the ovary." (PMID 27060927, 2016). "To further confirm the regulation of MDR1 expression by CDX2 in ovarian mucinous adenocarcinoma cells, we inhibited CDX2 expression by RNA interference (RNAi) and determined the effect on MDR1 transcript and protein expression." (PMID 27060927, 2016). "CDX2 expression was observed in ovarian mucinous adenocarcinoma with well‐ and moderately differentiated types, whereas expression was negative or faint in other histological types." (PMID 27060927, 2016). "For this experiment, we used OMC‐1, an ovarian mucinous adenocarcinoma cell line with high endogenous expression of CDX2 and MDR1." (PMID 27060927, 2016). "In conclusion, our findings demonstrated that MDR1 expression is regulated by CDX2 and is related to drug resistance in ovarian mucinous adenocarcinoma." (PMID 27060927, 2016). "MDR1 upregulation by aberrant CDX2 expression could be related to drug resistance observed in ovarian mucinous adenocarcinoma, a conclusion arising from the following observations." (PMID 27060927, 2016). "In addition, we investigated MDR1 regulation by CDX2 and MDR1‐associated drug resistance in ovarian mucinous adenocarcinoma cells." (PMID 27060927, 2016). "In ovarian mucinous adenocarcinoma, no reports have described an association between the expression of CDX2 and MDR1 and the degree of cancer cell differentiation." (PMID 27060927, 2016). "However, CDX2 can be seen in mucinous ovarian adenocarcinoma." (PMID 18801162, 2008). "In general, the typical primary mucinous ovarian carcinomas are CK7-positive, with diffuse co-expression of CK20 and CDX2, PAX8 and SATB2-negative, while AMNs are CDX2, CK20, and SATB2-positive, and PAX8 and CK7-negative." (PMID 40475008, 2025). "Using ovarian mucinous adenocarcinoma cell lines, we also observed decreased MDR1 expression following inhibition of CDX2 by RNA interference." (PMID 27060927, 2016). "We found that expression of CDX2 correlated with MDR1 expression and the degree of differentiation of ovarian mucinous adenocarcinoma cells." (PMID 27060927, 2016). "Our findings show that CDX2 promotes upregulation of MDR1 expression, leading to drug resistance in ovarian mucinous adenocarcinoma." (PMID 27060927, 2016). "In this study, we observed that CDX2 and MDR1 are expressed in ovarian mucinous adenocarcinoma and correlate with the degree of cancer cell differentiation." (PMID 27060927, 2016). "We further investigated the correlation of CDX2 and MDR1 expression in ovarian mucinous adenocarcinoma cell lines." (PMID 27060927, 2016). "The diffuse CK7 positive and CK20 and CDX2 negative immunostaining pattern also supported a primary ovarian mucinous carcinoma." (PMID 31279332, 2019). "CDX2 is a sensitive marker for mCRC, but it is non-specific and can also be expressed in ovarian mucinous carcinoma." (PMID 28730323, 2017). "In ovarian mucinous adenocarcinoma, our immunohistochemical staining results suggested a correlation between CDX2 and REG IV expression (data not shown)." (PMID 27060927, 2016). "Although further studies on MDR1 function and its regulation by CDX2 are required to elucidate the complex drug resistance mechanism, our results demonstrate the potential of novel chemotherapy regimens based on CDX2 status and MDR1 expression in ovarian mucinous adenocarcinoma." (PMID 27060927, 2016). "Therefore, our study demonstrates the potential of novel chemotherapy regimens based on CDX2 status and MDR1 expression in ovarian mucinous adenocarcinoma." (PMID 27060927, 2016).
ovarian mucinous carcinoma (continued). "It is possible that other factors besides CDX2 are required for activation of MDR1 transcription in certain settings, such as in MN‐1 cells, as MDR1‐positive ovarian mucinous adenocarcinoma cell lines (namely MN‐1) did not express CDX2 mRNA or protein." (PMID 27060927, 2016). "In line with the latest findings, Lee has recommended using a panel of CK7, CK20, CDX2, MUC2, 34βE12, and β-catenin to assist in the discrimination of urachal adenocarcinoma metastasis from primary ovarian mucinous carcinoma, and metastatic carcinoma from other organs." (PMID 23914849, 2013). "However, we have not yet confirmed whether CDX2 directly regulates MDR1 expression in ovarian mucinous adenocarcinoma cell lines." (PMID 27060927, 2016).
intestinal tumors (12 papers, 2001 to 2025). "Mouse models with Cdx2 null and Braf p.V600E alleles develop intestinal tumours with serrated phenotype and synergistic gene expression effects, such as a hundred-fold increase in the amount of the gastric epithelium marker Anx10a protein." (PMID 38439814, 2024). "To further investigate the malignancy of the intestinal tumours, we performed IHC staining for CDX2." (PMID 37962020, 2023). "We verified that the liver metastases originated from primary intestinal tumors by CDX2 staining." (PMID 39808497, 2025). "Furthermore, Cdx2 heterozygous null mice develop multiple intestinal tumours." (PMID 11161380, 2001).
metastatic carcinoma (12 papers, 2013 to 2025). A carcinoma which has spread from the original site of growth to another anatomic site. "The most well-known marker for metastatic carcinomas of gastrointestinal (GI) origin is CDX2 (Caudal Type Homeobox 2), a nuclear transcription factor that plays a role in intestinal epithelial cells proliferation and differentiation." (PMID 33504059, 2021). "The lack of CK7 expression and uniform immunoreactivity for CK20 and CDX2 supports a diagnosis of metastatic carcinoma of colorectal origin." (PMID 32164210, 2020). "For the identification of the primary site of metastatic cancer, immunohistochemistry using CD7, CD20, and CDX2 has become a useful examination." (PMID 37872388, 2023). "Not surprisingly, the metastatic carcinomas have the same CDX2 expression pattern as those of primaries." (PMID 24489794, 2014). "The metastatic carcinoma in lymph nodes show the identical CDX2 expression patterns as those of primary PDACs, with a 100% concordance on CDX2 expression between primary and metastatic PDAC, demonstrating that PDAC retains CDX2 expression after lymph node metastasis." (PMID 24489794, 2014). "To exclude ovarian or pancreatic metastatic cancer, we added markers of ovarian and pancreatic origin, including CK20, CA19-9, CDX-2, Villin and PAX8, all of which were negative." (PMID 36737820, 2023). "IHC study results showed positive reaction with CK20 and CDX2 and negative staining with CK7, PAX8, ER, and PR confirmed the colorectal origin of metastatic carcinoma." (PMID 36110333, 2022). "Additionally, positive staining for GATA-3 and GCDFP-15 confirmed the breast origin of the metastatic carcinoma, while negative staining for markers such as PAX-8 and CDX2 helped exclude primary ovarian and gastrointestinal origins, respectively." (PMID 41332036, 2025).
leukemia (11 papers, 2014 to 2024). A malignant (clonal) hematologic disorder, involving hematopoietic stem cells and characterized by the presence of primitive or atypical myeloid or lymphoid cells in the bone marrow and the blood. "Abnormal expression of the homeodomain transcription factor caudal‐related homeobox gene‐2 (CDX2) is associated with poor prognosis of leukemia patients." (PMID 33960108, 2021). "Moreover, individual analysis of CDX2 has limited applicability for the identification of this molecular subtype, but CDX2 overexpression has been reported in other leukemias associated with aberrant HOX gene expression." (PMID 39682152, 2024). "Beyond embryogenesis, pathological alterations of CDX2 levels occur at its physiological site of expression, the gut, as well as ectopically in the upper digestive tract and in leukemia." (PMID 34759958, 2021). "Cdx2-driven leukemia is sensitive to azacitidine, with enhanced sensitivity when administered at a lower-dose on an extended schedule in comparison to a higher-dose on a shorter schedule." (PMID 32541670, 2020). "In transplant experiments of Scl:Cdx2 secondary leukemias, we find that Aza prolongs survival of mice compared with vehicle treated controls, and Aza is preferentially toxic to Cdx2-mCherry-positive cells." (PMID 32541670, 2020). "There was increased apoptosis of Aza-treated Cdx2 cells, showing direct cytotoxicity of Aza on leukemia cells, with minimal effects on WT support cells or vehicle treated mice." (PMID 32541670, 2020). "Cellular studies have shown that Cdx2 confers oncogenic properties to murine hematopoietic stem cells in vitro, while turning on its expression in vivo induces myelodysplastic lesions, a few of them evolving into overt leukemia." (PMID 33960108, 2021). "The evolution of MDS to AL in Scl:Cdx2 mice with an expansion of mCherry-expressing c-Kit+ cells is likely due to the acquisition of transformation events and is consistent with secondary leukemia after MDS observed in patients." (PMID 32541670, 2020). "Furthermore, we used RNA-Seq profiles of each Cdx2-expressing leukemia to identify differentially expressed genes that were upregulated in T-ALL (#882) and B/T-ALL (#252) but not other samples." (PMID 32541670, 2020). "Given the importance of maintaining the balance between self-renewal and differentiation in HSPCs and LSCs, thorough investigation of these aberrant processes in Scl:Cdx2 cells may identify key regulators of leukemia evolution." (PMID 32541670, 2020). "Leukemia, another cancer in which Cdx2 is ectopically expressed, may have mechanistic parallels with epithelial cancers in terms of stress-induced reprogramming." (PMID 31739541, 2019). "Therefore, understanding targets of CDX2 in hematological malignancy and mechanisms of transformation may provide new opportunities to treat patients with leukemia." (PMID 32541670, 2020). "Thus CDX2 is one of the most frequently expressed proto-oncogenes in human leukemia." (PMID 31739541, 2019). "Interestingly, CDX2 expression also contributes to worse prognosis in leukemia." (PMID 24489794, 2014). "Besides, we have previously reported that the level of CDX2 has an impact on the cellular and molecular microenvironment in the intestinal epithelium, and the present study shows that it also has an effect on the way leukemia cells respond to an extracellular signaling molecule, namely TGF‐β." (PMID 33960108, 2021). "Overexpression of CDX2 is often observed in AML patients and is sufficient to induce leukemia in murine BM transplantation models." (PMID 34944554, 2021). "The caudal-related homeobox transcription factor CDX2 is expressed in leukemic cells in the majority of patients with leukemia but not during normal blood formation." (PMID 32541670, 2020). "Cdx2 alters HSPC identity and confers pre-leukemic progenitor cell characteristics, facilitating clonal evolution with important biological correlates of human leukemia." (PMID 32541670, 2020).
leukemia (continued). "We did not observe leukemia cooperativity between Scl:Cdx2 and Flt3ITD/+ models." (PMID 32541670, 2020). "However, this is not the case for another cancer in which Cdx2 is ectopically expressed—leukemia." (PMID 31739541, 2019).
hepatocellular carcinoma (10 papers, 2011 to 2025). A malignant tumor that arises from hepatocytes. "CDX2 expression was higher in metastatic than in primary CRC cells, and absent in hepatocellular carcinoma." (PMID 31903162, 2019).